SIRT1 (sirtuin 1)
Diseases named in the same sentence as SIRT1 in open-access papers (continued):
Sharing a sentence is not in itself a finding about the gene and the disease.
pulmonary fibrosis (continued). "SIRT1 is a multifunctional protein shown to be involved in fibrosis and aging of various organs, with particularly contradictory results in BLM-induced lung fibrosis." (PMID 32630813, 2020). "Thus, SIRT1 may mediate, miR34a-regulated, persistent FLIP levels by deacetylation of Ku70 in lung myofibroblasts, promoting resistance to cell-death and lung fibrosis." (PMID 32630813, 2020). "Our studies suggest that inhibition of miR34a-mediated SIRT1 activity, specifically on mesenchymal cells, may play a role in the mechanism affecting FLIP stability, and myofibroblast escape from immune surveillance with subsequent accumulation and lung fibrosis." (PMID 32630813, 2020). "We also examined the positive correlation between the SIRT1 and AROS protein expression levels using IHC data from a human pulmonary fibrosis tissue microarray (data not shown)." (PMID 37258580, 2023).
chronic obstructive pulmonary disease (44 papers, 2011 to 2025). A chronic and progressive lung disorder characterized by the loss of elasticity of the bronchial tree and the air sacs, destruction of the air sacs wall, thickening of the bronchial wall, and mucous accumulation in the bronchial tree. "CD8+ T and natural killer T cell(NKT)-like cells in patients with chronic obstructive pulmonary disease (COPD) show glucocorticoid resistance associated with decreased SIRT1 expression." (PMID 40416964, 2025). "Sirt1 expression has been shown to attenuate inflammatory responses in chronic obstructive pulmonary disease (COPD), cardiac hypertrophy, and inflammation-associated liver diseases." (PMID 32373350, 2020). "It has also been reported that nucleosides inhibit chronic obstructive pulmonary disease inflammation and maintain lung function by upregulating the SIRT1-NF-κB/p65 pathway." (PMID 39195510, 2024). "Rajendrasozhan S., Yang S.R., Kinnula V.L., Rahman I. SIRT1,an antiinflammatory and antiaging protein, is decreased inlungs of patients with chronic obstructive pulmonary disease.Am." (PMID 37867611, 2023). "Resveratrol targets the PGC-1α pathway through activation of SIRT1, and has been found to decrease oxidative stress in the lungs of chronic obstructive pulmonary disease (COPD) patients." (PMID 36293464, 2022). "Senescent T-lymphocytes are demonstrated with reduced SIRT-1 specifically in the CD28−CD8+ T-cells contributing to chronic obstructive pulmonary disease (COPD)." (PMID 36361845, 2022). "Cathepsin S (CTSS) and Sirtuin-1 (SIRT1) played crucial roles in the pathogenesis of chronic obstructive pulmonary disease (COPD)." (PMID 29976774, 2018). "Because of this, it would also be interesting to explore the benefits of SIRT1 modulators in age-associated diseases, which share an inflammatory base and high levels of oxidative stress, such as COPD (chronic obstructive pulmonary disease) or Alzheimer’s disease." (PMID 32485811, 2020). "By diminishing TGF-β1 activity, apoptosis, and endoplasmic reticulum stress via Sirtuin-1 upregulation in animal studies, melatonin could be protective in chronic obstructive pulmonary disease (COPD)." (PMID 32825327, 2020). "Additionally, a previous study suggested that melatonin protected against chronic obstructive pulmonary disease by preventing apoptosis and ER stress through the upregulation of SIRT1 expression in rat bronchial and alveolar epithelial cells." (PMID 31450679, 2019). "Because of a significant reduction of SIRT1 in rodent lungs exposed to cigarette smoke and in lungs of patients with chronic obstructive pulmonary disease (COPD), activation of SIRT1 may be a potential target for chronic obstructive pulmonary disease therapy." (PMID 23774840, 2013). "In patients with chronic obstructive pulmonary disease (COPD), reduced SIRT1 expression in immune cells correlates with diminished corticosteroid sensitivity." (PMID 41376865, 2025). "In chronic obstructive pulmonary disease (COPD), SIRT1 activity and nuclear expression are decreased, promoting NF-κB direction to the IL-8 gene promoter." (PMID 35359990, 2022). "SIRT1 expression has positive effects in many diseases, including cancer, CVDs, chronic obstructive pulmonary disease (COPD), and type 2 diabetes." (PMID 34490241, 2021). "We evaluated the effects of melatonin on inflammatory response in chronic obstructive pulmonary disease (COPD), focusing on the regulation of SIRT1 expression." (PMID 31762195, 2020). "In other conditions, such as chronic obstructive pulmonary disease (COPD), physical exercise ameliorates clinical symptoms and increases Sirt1 activity that negatively regulate NFκB pathway and metallo-proteinases secretion significantly decreasing inflammation." (PMID 30304806, 2018).
chronic obstructive pulmonary disease (continued). "Apart from protecting against endothelial senescence, SIRT1 also plays a key role in preventing stress-induced premature senescence (SIPS) and lung inflammaging, one of the hallmarks of chronic obstructive pulmonary disease (COPD) or emphysema." (PMID 25907989, 2015). "In chronic obstructive pulmonary disease (COPD), the level of metalloproteinases-9 (MMP9) might increase in consequence of Sirt1 reduction." (PMID 33121118, 2020). "Sirtuin-1 (SIRT1) and SIRT6, NAD+-dependent Class III protein deacetylases, are putative anti-aging enzymes, down-regulated in patients with chronic obstructive pulmonary disease (COPD), which is characterized by the accelerated ageing of the lung and associated with increased oxidative stress." (PMID 27767101, 2016). "In humans, moderate physical activity time positively correlated with SIRT1 and FOXO1 mRNA expression in PBMCs in chronic obstructive pulmonary disease (COPD) patients." (PMID 39264516, 2024). "This PDE4 inhibitor is typically used in the treatment of chronic obstructive pulmonary disease (COPD) and in this case acts by the indirect inhibition of PTP1B, with the effects mediated by the crosstalk between the CREB/BDNF/TrkB and SIRT1/PTP1B/IGF1 signaling pathways." (PMID 39000142, 2024). "SIRT1 was found to induce ECM degradation by deacetylating histones on the MMP9 promoter, thereby suppressing its transcription in chronic obstructive pulmonary disease (COPD)." (PMID 36864460, 2023). "Downregulated expression levels of SIRT1 and TBX-3 have also been observed in lung specimens derived from chronic obstructive pulmonary disease, which indicated that SIRT1 and TBX-3 are not always negatively regulated." (PMID 32627000, 2020).
bladder cancer (43 papers, 2013 to 2026). "Our study for the first time suggested that SIRT1 deficiency in bladder cancer cells could suppress proliferation and ROS production, as well as induce cell cycle arrest, possibly via the FOXO3a-mediated pathways." (PMID 29147649, 2017). "In summary, our findings demonstrate that TACC3-PCAF competes with SIRT1 to bind c-Myc, enhancing its acetylation at K323 and thereby stabilizing c-Myc to promote colony formation and proliferation in bladder cancer." (PMID 40246827, 2025). "Given that heliomycin was previously reported to target and downregulate SIRT1 in bladder cancer cells, in this present study, we addressed the question of SIRT1 inhibition by 4-dmH and its associated molecular events." (PMID 38567911, 2024). "Our results also demonstrated that heliomycin treatment downregulated SIRT1 expression and that the binding of heliomycin to SIRT1 triggered autophagy to repress the growth of bladder cancer cells." (PMID 38567911, 2024). "Our group has explored the anticancer properties of heliomycin and established its binding with SIRT1 in the native cellular environment of bladder cancer cells." (PMID 38567911, 2024). "In summary, our study elucidated that SIRT1 promotes cisplatin resistance in human bladder cancer T24 cells through Beclin1-deacetylation-mediated autophagy activation." (PMID 38201552, 2023). "For example, high expression of sirtuin 1 significantly promoted the proliferation of bladder cancer cells." (PMID 33162827, 2020). "A recent study suggested that TM4SF1 can regulate apoptosis and the cell cycle via the PARγ-SIRT1 feedback loop in bladder cancer cells." (PMID 33153498, 2020). "In bladder cancer, TM4SF1 deficiency significantly upregulated PPARγ and forkhead transcription factor 3a (FOXO3a) and downregulated SIRT1 protein expression, forming a feedback loop that modulates the cell cycle." (PMID 33015133, 2020). "The regulatory ability of the PPARγ-SIRT1 feedback loop explains the tumor promoting effect of TM4SF1 on bladder cancer." (PMID 32328200, 2020). "Our results, together with previous studies, revealed that the PPARγ-SIRT1 feedback loop mattered greatly in ROS metabolism in bladder cancer." (PMID 32328200, 2020). "In accordance, SIRT1 knockout has proved able to suppress bladder cancer cell proliferation, viability and migration, and also reduce the EMT program potency." (PMID 30875794, 2019). "Capsaicin reduces bladder cancer cell migration by direct binding with sirtuin 1 (SIRT1) followed by down-regulation of SIRT1 deacetylase." (PMID 31600949, 2019). "Our further investigation in human bladder tissue samples at a larger scale revealed that SIRT1 possessed an overexpression in human bladder cancer tissues than in paracancerous tissues or normal bladder tissues, at both transcriptional and protein levels." (PMID 29147649, 2017). "Here, we report that capsaicin-mediated tNOX suppression and experimental knockdown of tNOX reduce SIRT1 expression in a bladder cancer cell line." (PMID 27367652, 2016). "Taken together, our results indicate that capsaicin inhibits the growth of bladder cancer cells by inhibiting tNOX and SIRT1 and thereby reducing proliferation, attenuating migration, and prolonging cell cycle progression." (PMID 27367652, 2016). "For example, in bladder cancer cells, Capsaicin reduces the deacetylase of SIRT1, enhances the acetylation of cortactin and β-catenin, thereby reducing the activation of MMP-2 and MMP-9, and ultimately leads to the migration disturbance of bladder cancer cells." (PMID 40007993, 2025). "Very recently, SIRT1 was shown to function as a cellular target for heliomycin, and this targeting was identified as being important for the anticancer activity of heliomycin in bladder cancer cells." (PMID 38567911, 2024).
bladder cancer (continued). "Interestingly, the regulation of ROS production by HJURP varies in different kinds of cancer: HJURP inhibits ROS production via the PPARγ-SIRT1 feedback loop in bladder cancer, while it enhances ROS stress in renal cell carcinoma." (PMID 39405980, 2024). "However, in another study, a notable SIRT1 upregulation in bladder cancer (as compared to matched control) tissues was observed, thus indicating its oncogenic role in urothelial malignancies." (PMID 30875794, 2019). "Therefore, SRT1720, a SIRT1 activator, can significantly inhibit the growth of bladder cancer cells and may become a new method for treating bladder cancer." (PMID 39778006, 2025). "Therefore, we speculate that SIRT1 could promote cisplatin resistance in bladder cancer by activating autophagy, but the mechanism of its mediation of autophagy activation in T24/DDP cell lines remains elusive." (PMID 38201552, 2023). "However, the specific mechanism through which SIRT1 mediates cisplatin resistance in bladder cancer via autophagy remains unclear." (PMID 38201552, 2023). "However, the role of SIRT1 in promoting chemoresistance has rarely been reported in bladder cancer." (PMID 38201552, 2023). "However, the precise mechanism through which SIRT1 mediates cisplatin resistance in bladder cancer via autophagy remains unclear." (PMID 38201552, 2023). "Therefore, this study selected the T24 cell line to establish the cisplatin-resistant T24/DDP cell line, aiming to deeply explore the potential mechanism through which the SIRT1–Beclin1 pathway regulates autophagy-dependent cisplatin resistance in bladder cancer." (PMID 38201552, 2023). "In addition, our group found that HJURP could have an impact on the PPARγ-SIRT1 feedback loop, regulating ROS metabolism, and resulting in the progression of bladder cancer." (PMID 32328200, 2020). "SIRT1 mutation promotes cancer proliferation and diminishes their sensitivity to SRT1720, supporting SIRT1 as a direct and relevant target of SRT1720 in bladder cancer." (PMID 41304967, 2025). "Conversely, SIRT1 overexpression has been found to upregulate GLUT1 transcription and promote both cell proliferation and glycolysis in bladder cancer cells." (PMID 38178094, 2024). "Using a cellular thermal shift assay (CETSA) in T24 bladder cancer cells, we show that capsaicin directly engages with tNOX, and that this binding inhibits NAD+ generation and downregulates tNOX, which suppresses sirtuin-1 (SIRT1) deacetylase activity." (PMID 31635402, 2019). "We further discuss the emerging evidence that natural products can modulate acetylation-related pathways in bladder cancer, mainly through targeting HDAC-dependent histone deacetylation and SIRT1-associated non-histone deacetylation." (PMID 42193094, 2026). "In conclusion, we found that the deacetylase SIRT1 is highly expressed in T24/DDP cell lines, and can mediate protective autophagy activation through Beclin1 deacetylation, subsequently promoting cisplatin resistance in bladder cancer." (PMID 38201552, 2023). "Holliday junction recognition protein (HJURP) is a centromeric histone chaperone that also acts on the PPARγ-SIRT1 negative feedback loop, impacting on cell proliferation and apoptosis in bladder cancer." (PMID 32328200, 2020). "This is consistent with a study in bladder cancer, where knockdown of Cdk6 and SIRT-1 (direct targets of miR-34a) was not as effective reversing cisplatin resistance as miR-34a restoration." (PMID 35582270, 2019). "SIRT1 is reported to play a role in the metabolism of the reactive oxygen species (ROS) in cells, but how SIRT1 affected ROS metabolism in bladder cancer cells has not been reported yet." (PMID 29147649, 2017). "For further discussion, it is reported that the overexpression of Thromboxane-A2 isoform-β receptor (TPβ) plays an important role in the process of human bladder cancer, and TP agonist decreased acetylation of FOXO3 via upregulation of SIRT1 in the bladder cancer cell line UMUC3." (PMID 29147649, 2017).
bladder cancer (continued). "Knockdown experiments provided evidence that HJURP could regulate bladder cancer cell’s proliferation and apoptosis via the PPARγ-SIRT1 negative feedback loop." (PMID 31847118, 2019).
rheumatoid arthritis (43 papers, 2013 to 2026). A chronic, systemic autoimmune disorder characterized by inflammation in the synovial membranes and articular surfaces. "Research has determined that SIRT1 expression and activity are down in patients with chronic inflammatory diseases such as rheumatoid arthritis and inflammatory bowel disease, which are associated with the long-term activation of ER stress and the NF-kB signaling pathway." (PMID 38745862, 2024). "Preclinical and clinical studies have demonstrated the importance of SIRT1 in the pathogenesis of autoimmune diseases, including rheumatoid arthritis, systemic lupus erythematosus, inflammatory bowel disease, multiple sclerosis, and others." (PMID 40757915, 2025). "Resveratrol can also regulate the nuclear factor kappa-B signalling pathway via SIRT1 to reduce inflammatory cell infiltration in the joint cavity of rheumatoid arthritis (RA) and/or OA while inhibiting synovial cell proliferation." (PMID 39055794, 2024). "In rheumatoid arthritis animal models, SIRT1 overexpression or administration of SIRT1 activators can markedly suppress the ER stress and the NF-κB activation of synovial cell, which basically decreased synovial inflammation and cartilage destruction." (PMID 38745862, 2024). "The modulation of SIRT proteins, particularly SIRT1 activity, appears to be important in the pathogenesis of rheumatoid arthritis." (PMID 36675041, 2023). "SIRT1 affects many types of cells involved in the development and progression of rheumatoid arthritis, such as chondrocytes, synovial fibroblasts (FLs), macrophages, and T cells (Tc)." (PMID 36675041, 2023). "Resveratrol improves rheumatoid arthritis by activating SIRT1-Nrf2 signaling pathway and autophagy, and plays a beneficial role in mitochondrial function by activating AMPK." (PMID 35047575, 2021). "Res, a silence information regulator 1 (SIRT1) activator, induces apoptosis MH7A human rheumatoid arthritis synovial cells in a SIRT1-dependent manner." (PMID 32397765, 2020). "SIRT1 was reported to regulate the development of rheumatoid arthritis through interaction with HIF-1." (PMID 32347300, 2020). "Previous studies have shown that SIRT1 is involved in diabetic kidney disease and rheumatoid arthritis." (PMID 32485674, 2020). "In rheumatoid arthritis, SIRT1/adenosine monophosphate enhances anti-inflammatory M2 macrophage polarization by activating AMPK signaling." (PMID 33363533, 2020). "Resveratrol, a SIRT1 activator, serves as an anti-inflammatory compound and can alleviate various inflammatory diseases, such as rheumatoid arthritis and type I diabetes." (PMID 30622543, 2018). "Resveratrol induces apoptosis MH7A human rheumatoid arthritis synovial cells in a sirtuin 1-dependent manner." (PMID 26273643, 2015). "Resveratrol, a Silence Information Regulator 1 (SIRT1) activator, induces apoptosis MH7A human rheumatoid arthritis synovial cells in a SIRT1-dependent manner." (PMID 26273643, 2015). "Mechanistically, hsa_circ_0044235 ameliorates rheumatoid arthritis (RA) progression through the miR‐135b‐5p/SIRT1 axis, demonstrating anti‐inflammatory and antipyroptotic effects in both collagen‐induced arthritis mouse models and fibroblast‐like synoviocytes (FLSs)." (PMID 41284375, 2025). "Taken together, suppression of TNF-β-induced inflammatory microenvironment in PCH by resveratrol/Sirt1 might be a novel therapeutic approach for targeting inflammation during rheumatoid arthritis." (PMID 29095837, 2017). "In agreement with this hypothesis, inhibition of Sirt1 enzymatic activity reduces LPS-induced levels of TNF in monocytes of patients with rheumatoid arthritis." (PMID 25799392, 2015). "In agreement with this hypothesis, inhibition of Sirt1 enzymatic activity reduces LPS-induced levels of TNFα in monocytes of patients with rheumatoid arthritis." (PMID 23844973, 2013). "However, it is unknown whether SIRT1 has a role in the tumor-like invasion of FLSs in rheumatoid arthritis." (PMID 29179491, 2017).